KIT (KIT proto-oncogene, receptor tyrosine kinase)
Diseases named in the same sentence as KIT in open-access papers (continued):
Sharing a sentence is not in itself a finding about the gene and the disease.
tumor (continued). "After identifying specific genetic mutations in the tumor, it is possible to tailor systemic therapy using drugs that target these mutations, such as BRAF, MEK, KIT inhibitors, or checkpoint inhibitors." (PMID 40344340, 2025). "Imatinib’s efficacy in GISTs stems from its ability to inhibit two key receptor tyrosine kinases, c-KIT and PDGFRA, both of which are frequently mutated in these tumours." (PMID 41426918, 2025). "In previous years, we tried to expand the platform by collecting several PDGFRA-mutated tumor samples and tumor samples of the historically called ‘wild-type’ genotype, i.e. GIST with mutations other than KIT or PDGFRA." (PMID 39853155, 2025). "By inhibiting c-KIT, imatinib induces apoptosis in tumour cells, effectively reducing tumour burden and limiting disease progression." (PMID 41426918, 2025). "Results reveal that ApDC targets GIST by specific binding with KIT and subsequently internalizes into tumor cells to release the drug." (PMID 40963922, 2025). "Tumor cells of eo-ChRCC proliferate in a solid pattern, exhibit raisnoid nuclei with irregular contour and are usually positive for KIT." (PMID 39980061, 2025). "Conversely, while KIT mutant cases showed an equal distribution in primary tumor site, NF1-mutant cases had an exclusive small intestine localization (9/9), and PDGFRA-mutant cases had gastric localization only (18/18)." (PMID 41407759, 2025). "Cyclin D1 was shown to be overexpressed in KIT-independent GISTs, indicating its function in tumor proliferation and resistance when KIT signaling is lost." (PMID 41189865, 2025). "Summary of existing guidelines for recommendations of SDHB immunohistochemistry (IHC) and molecular tumor analysis, and timing in relation to KIT/PDGFRA testing." (PMID 39927693, 2025). "Given our earlier experimental data indicating the significant inhibitory effect of KIT-d-MMAE on tumor migration, we further developed a GIST liver metastasis model with GIST-T1 cell to assess the potential of ApDC in tumor metastasis inhibition." (PMID 40963922, 2025). "Several important prognostic factors, such as tumor size and the anatomical location of the GIST, showed similar distributions across both KIT-exon 11 and non-KIT-exon 11 mutated GIST groups." (PMID 40002229, 2025). "HLA-A staining followed a similar pattern to that of PDE3A and KIT staining, suggesting that the tumor cells were efficiently eliminated with SC ANA treatment, allowing the host animal cells – in this case, mouse – to re-populate the remaining space." (PMID 39930717, 2025). "Immunohistochemical studies have found that 15–30% of all NBs are KIT-positive, while PCR data suggest that KIT is expressed in 40–80% of these tumours, depending on the specific study, and about half of KIT-positive NB tumours also express SCF." (PMID 41511287, 2025). "In animal studies, KIT-d-MMAE significantly suppressed tumor growth in GIST-T1 subcutaneous and liver metastasis models." (PMID 40963922, 2025). "A meta-analysis including 1,487 GIST patients found that the KIT mutations compared with PDGFRA mutations and wild-type tumors were associated with an increased risk of tumor size of >5 cm and higher mitotic activity." (PMID 40703587, 2025). "The occurrence of KIT positivity in tumor samples was significantly lower than expected, with rates of 21% compared to the anticipated 70%." (PMID 39858036, 2025). "Approximately 85% of GISTs harbor mutually exclusive activating mutations in KIT (exons 9, 11, 13, 17) or PDGFRA (exons 12, 18), driving constitutive receptor tyrosine kinase (RTK) activation and tumor progression." (PMID 40900786, 2025). "Most original tumor samples showed KIT positivity in immunohistochemical (IHC) analysis (65 tumor samples; 85.5%)." (PMID 39853155, 2025).
tumor (continued). "VEGFRs, PDGFRs, and stem cell factor receptor (KIT) are tyrosine kinases that play pivotal roles in regulating tumor proliferation and angiogenesis." (PMID 41511285, 2025). "PDGFRA‐mutant GISTs, compared to KIT‐mutant GISTs, have more T cells and exhibit a stronger tumour‐killing ability, while wtGISTs show less immune infiltration." (PMID 41230918, 2025). "As a multi-targeted tyrosine kinase inhibitor that blocks VEGFR, PDGFR, and c-KIT, pazopanib reduces angiogenesis and can transiently normalize the tumor vasculature." (PMID 41211443, 2025). "The KIT-d-MMAE group demonstrated a substantial reduction in tumor weight, about 56% tumor inhibition rate (p = 0.0071) compared to the DPBS group, along with significantly lower Ki67 levels." (PMID 40963922, 2025). "Therapeutically, the advent of KIT-targeted tyrosine kinase inhibitors like imatinib provided proof that a subset of these patients can achieve meaningful tumor regressions." (PMID 41301010, 2025). "Genotypically, most GISTs are driven by activating mutations in the tyrosine kinase receptors, KIT and platelet-derived growth factor receptor alpha (PDGFR-α), leading to uncontrolled cell proliferation and tumor growth." (PMID 40417261, 2025). "Pazopanib is an oral, selective TKI that targets VEGFR1-3, PDGFR, and c-KIT, resulting in significant inhibition of angiogenesis and tumor cell proliferation." (PMID 41395622, 2025). "In parallel, tumor-bearing mice received repeated doses of KIT-d-MMAE (4 mg/kg) to evaluate long-term toxicity in a therapeutic context." (PMID 40963922, 2025). "TT with imatinib was administered in a single case of GIST, KIT-amplified, which allowed short-term stabilization of the tumor." (PMID 41373618, 2025). "CD117-positive cells were shown inside the muscle tissue in the tumor by immunostaining with anti-c-KIT antibodies." (PMID 40094003, 2025). "Single-cell RNA sequencing analysis further revealed that NOTCH signaling components, such as GALNT11, HES1, KIT, and SLC35C1, are significantly upregulated in tumor-associated monocytes/macrophages." (PMID 40361382, 2025). "Acting primarily as a ligand by binding to c-KIT, it presents significant biological activities on an array of tissue cells, including hematopoietic stem cells, pigment cells, germ cells, and tumor cells." (PMID 38213737, 2024). "In MCC tumor cell lines, KIT was found to be activated via an autocrine mechanism through the co-expression of KIT and its ligand SCF." (PMID 39456853, 2024). "First, tumour adaptation to KIT/PDGFRA inhibition likely leads to apoptosis evasion and GISTs survival through two intertwined events." (PMID 39070147, 2024). "SDC1 exhibited a greater tumor mutational burden (TMB) score, while ERBB2, KDR, FGF2, KIT, FGFR1, and FGF1 showed lower TMB scores." (PMID 38189813, 2024). "The intra‐tumour heterogeneity of KIT in single‐site MCTs and the presence of multiple subclones have been previously reported in feline MCTs." (PMID 39177283, 2024). "KIT functions as a proto-oncogene via its kinase activity, as well as a tumor suppressor via its receptor activity." (PMID 38396943, 2024). "The cultured tumor cells expressed cytokeratins, p63, and CD117/KIT and were tumorigenic in nude mice." (PMID 39123489, 2024). "For the proband, somatic sequencing identified a variant allele fraction of 58% (KIT) and 63% (MSR1) within the one tumor and 61% (KIT) and 50% (MSR1) within the second tumor analyzed." (PMID 38538628, 2024). "PPARD agonists promote the expression of platelet-derived growth factor receptor beta, platelet-derived growth factor subunit B, and the tyrosinkinase KIT to promte tumor angiogenesis and progression." (PMID 38212774, 2024). "KIT/PDGFRA WT-GISTs are a genomically heterogeneous group of neoplasms, representing 10–15% of all GISTs." (PMID 39199677, 2024). "Histologic grading and immunohistochemical staining for Ki-67 and KIT patterns were performed on excised tumor specimens." (PMID 39765802, 2024).
tumor (continued). "Among MM drivers, somatic mutations of NRAS and the TERT promoter are reported, as well as mutually exclusive loss of function mutation of the tumor suppressors NF1 and SPRED1, the latter co-occurring with activating KIT mutations." (PMID 38191367, 2024). "For the proband’s mother, somatic sequencing demonstrated variant allele fractions of 47% (KIT) and 51% (MSR1) within one tumor and 55 and 57% within the second tumor analyzed for KIT and MSR1, respectively." (PMID 38538628, 2024). "Small molecules against MOZ or Menin remarkably reduced GIST tumor growth with synergistic toxicity in vivo and in vitro with the combination of KIT inhibitors." (PMID 38414063, 2024). "The RAS/RAF/MEK/ERK, as well as the KIT-activated pathways, have been demonstrated to be efficiently druggable, providing new therapy tools to limit tumor progression, particularly in patients that develop resistance to platinum-based treatments." (PMID 38541652, 2024). "In another case study, a 92-year-old female with MCC received KIT-positive tumor-initiated therapy with imatinib 400 mg daily." (PMID 39456853, 2024). "CHIP-seq of GIST tumor samples and cell lines identified the enhancer domain to be driving KIT gene expression, which is unique and essential for KIT gene expression and cell viability in GIST." (PMID 38414063, 2024). "The high expression of IDO1, a gene expressed in KIT+ GIST tumor cells, was identified as an important mechanism for imatinib resistance." (PMID 38443340, 2024). "In this study, we investigated the role of the zinc finger protein ZSWIM4 in GISTs, and our results suggested that ZSWIM4 serves as a tumor suppressor in GISTs by inhibition of KIT signaling." (PMID 38951864, 2024). "KIT is the master regulator controlling the switching to a permissible scenario for tumor proliferation." (PMID 39031010, 2024). "As imatinib, a tyrosine kinase inhibitor, exerts anti‐tumour effects on feline MCTs harbouring KIT exon 8 or 9 ITD via the inhibition of phosphorylation, the treatment response to toceranib in this case was assessed using a similar mechanism." (PMID 39177283, 2024). "The correlation between downregulation of miRNA-221/222 and KIT expression was reported in several studies, indicating a tumor suppressor-miR in GIST." (PMID 38414063, 2024). "The increased c-KIT positivity in both basal tumor regions and normal LP cells further emphasizes the connection between these two cells from a proteomic view." (PMID 39478117, 2024). "We found a statistically significant correlation between TATE and Patnaik grading (p = 0.041), Kiupel grading (p = 0.022), immunohistochemical KIT expression (p = 0.015), and tumor recurrence (p = 0.000)." (PMID 36670824, 2023). "Unsurprisingly, the cutaneous form is the most widely studied, with various degrees of positive KIT labeling on immunohistochemistry (IHC) in 168/208 (81%; range: 55–93%) tumor samples across all reviewed studies." (PMID 37835664, 2023). "Completed studies on treatments targeting the KIT gene include anti-drug conjugates against small cell lung cancer and a DNA vaccine targeting ligand attachment to fight tumor growth." (PMID 37513844, 2023). "The tumor stained positively for CD117 (KIT) and was composed of mixed epithelioid/spindle cells with five mitoses/50 high-power fields." (PMID 37027098, 2023). "From the analysis of modified TATE classification, we observed a significant association with Patnaik grading (p = 0.041), Kiupel grading (p = 0.022), KIT expression (p = 0.015), and tumor recurrence (p = 0.000)." (PMID 36670824, 2023).
tumor (continued). "Thirty-six tumor samples from 19 BRAF V600+ and 17 BRAF V600− patients (three of whom had pathogenetic mutations in the KIT gene) were analyzed and their mutational profiles/CNV/LOH correlated with clinical response." (PMID 36901733, 2023). "Mutation of KIT or PDGFRA leads to constitutive kinase activation independent of the ligand, and consequent unrestrained induction of signalling cascades leading to tumour proliferation at an abnormally high rate." (PMID 36774883, 2023). "Of note, PDGFRA and KDR are not contiguous in the 4q12 amplicon, and the intermediate gene KIT was also found as singularly amplified in a subpopulation of one tumor." (PMID 37610648, 2023). "Nevertheless, it is remarkable that a high proportion of tumours had aberrant KIT patterns II and III, and many digital MCTs also had increased proliferation activity, as detected by Ki67." (PMID 37238124, 2023). "Lenvatinib targets the VEGF receptors 1–3, FGF receptors 1–4, PDGF receptor α, RET, and KIT and is an effective inhibitor of tumor angiogenesis." (PMID 36902316, 2023). "Recently, c‐KIT has been reported to be involved in thyroid cell differentiation and tumor progression." (PMID 37506147, 2023). "MYC+MEL cells were increased in LN+AM and expressed high levels of MYC, MITF, SNAI2, and KIT, all of which play crucial roles in tumor progression." (PMID 38065972, 2023). "Imatinib inhibits the proliferation and survival of GIST tumor cells primarily through suppressing KIT signaling pathway." (PMID 37072770, 2023). "The in vivo results of compound 75 in a Ba/F3 KIT-exon 11 del/D816H mouse allograft tumor model revealed that there was a 5% inhibition, and tumor size was not affected." (PMID 37298401, 2023). "The in vivo efficacy of 130d at a dosage of 100 mg/kg in a BaF3-TEL-c-KIT-T670I cell-inoculated xenograft mouse model displayed 41.9% tumor growth inhibition and a good safety profile." (PMID 37298401, 2023). "We performed WGS of 60 genomes from DNA isolated from tumor tissue and matched blood samples from 30 patients with GIST with pathogenic KIT mutations in exon 11 to identify the genomic characteristics contributing to the development of KIT Δ557–558 in GISTs." (PMID 37377752, 2023). "MGMT methylation analysis was performed on 68 tumour samples from 65 individual patients including 47 wtGIST (67.7%) and 21 (32.3%) TK mutant (17 KIT and 4 PDGFRA) GIST (30.9%)." (PMID 36198483, 2023). "c-KIT-dependent cell types include mast cells, specific haematopoietic stem cells, germ cells, melanocytes, and Cajal cells of the digestive system are all c-KIT-positive, including their tumour cells." (PMID 37928785, 2023). "It is also compared with overlying mucosa, histopathological features like the mitotic index, tumor grade, and immunohistochemistry features (c-KIT, DOG), which didn’t show any correlation with hemoglobin levels (p>0.05)." (PMID 37323307, 2023). "Over an 11-day course of treatment, compound 35h showed a dose-dependent inhibition of BaF3-tel-c-KIT-T670I tumor progression with almost 100% tumor growth inhibition at a dosage of 100 mg/kg/day." (PMID 37298401, 2023). "Unexpectedly, many digital MCTs had an aberrant immunohistochemical KIT pattern and were highly proliferative, despite a large proportion of low-grade tumours." (PMID 37238124, 2023). "Immunohistochemically, the tumor cells showed strong pancytoplasmic staining of the type III receptor tyrosine kinase (KIT) and the transmembrane protein discovered on GIST (DOG1) and negative staining for S100 and desmin." (PMID 37789344, 2023). "KIT acts on a targeted pathway that coordinates the number and activity of tumor innate immune cells." (PMID 37506147, 2023).
tumor (continued). "As TGFβ expression is induced following KIT overexpression and lost following KIT deletion, we tested how KIT expression influences canonical TGFβ signaling in tumor cells." (PMID 35842424, 2022). "In GISTs, KIT was also targeted directly by miRNA-218 and miRNA-148b-3p, which acted as tumor suppressors and sensitized GIST cells to imatinib therapy." (PMID 35174150, 2022). "KIT and PDGFRA are the main driver mutations but insufficient to promote tumor progression from low- to high-risk GISTs." (PMID 35965531, 2022). "NK subpopulations revealed a KIT+IL-7R+ progenitor subset that was suppressed within tumor but increased in patients who obtained good pathological response to NACT." (PMID 36253784, 2022). "The dependence of tumor cells on constitutively activated KIT/PDGFRA makes GIST a logical target for treatment with tyrosine kinase inhibitors (TKI)." (PMID 35625872, 2022). "Several studies have reported that receptor tyrosine kinase (RTK) KIT (CD117) is expressed in NB tumor cells along with its ligand SCF (stem cell factor)." (PMID 35887076, 2022). "Since in bulk tumor samples gene expression can be affected by tumor microenvironment and KIT can be expressed by immune cells, we analyzed the correlation between KIT expression and typical immune infiltration signatures for different cancer types." (PMID 35887076, 2022). "Overall, these data indicate that KIT is potentially one of the main targets for multikinase inhibitor drugs in NB tumor cells and is relevant for more aggressive tumors." (PMID 35887076, 2022). "Expression of c-KIT suggestive of differentiation of stem cells into spermatogonia was markedly reduced in the tumor sections." (PMID 35676718, 2022). "Previous research has used H3K27ac chromatin immunoprecipitation with sequencing (ChIP-seq) of GIST tumour samples and cell lines and identified the SE clusters that drive c-KIT gene expression and are unique to GISTs." (PMID 36076237, 2022). "NK populations within tumor were broadly comparable with normal tissue although the progenitor KIT population was suppressed but increased after chemotherapy in relation to the degree of pathological response, suggesting a potential role in tumor control." (PMID 36253784, 2022). "It is generally accepted that whereas oncogenic KIT and PDGFRA mutations are necessary for the neoplastic transformation of GIST, additional somatic genomic alterations are required for tumor progression." (PMID 35284037, 2022). "In conclusion, our study identifies high KIT expression as a third potential mechanism that is utilized by tumor cells to evade growth suppression by TGFβ, presumably by downregulating one of the core signaling components in the pathway, SMAD2." (PMID 35842424, 2022). "In a mouse colon-26 tumor model, inhibition of receptor tyrosine kinase KIT enhances the anti-tumor activity of immune checkpoint inhibitors (anti-CTLA-4 and anti-PD-1) by selectively reducing immunosuppressive M-MDSC clusters." (PMID 35740594, 2022). "Other published data suggest that KIT has a dual role in cancer, acting both as an oncogene via its kinase domain or as a tumor suppressor through induction of apoptosis." (PMID 36396684, 2022). "A small subpopulation of cancer stem cells characterized by high expression of c-KIT was detected from several tumor samples and cell lines." (PMID 34716856, 2022). "Western blot analysis of the expression of KIT-mediated signalling pathways in tumour tissues demonstrated that cabozantinib treatment also decreased p-KIT, p-STAT3, p-AKT, p-mTOR, and p-ERK1/2 expression levels in vivo." (PMID 33833412, 2022). "Although 11/36 (36.7%) tumour samples showed positive staining for c-KIT, in most of them only minimal staining was noted (<1% of cells)." (PMID 35324835, 2022). "This provides insight into how KIT protects tumor cells against the tumor suppressive effects of TGFβ." (PMID 35842424, 2022).